CMTM8 (CKLF like MARVEL transmembrane domain containing 8)
Synonyms: CKLFSF8; CKLFSF8-V2
Tractability: Antibody: UniProt predicts a signal peptide or a membrane-spanning region.
Gene: Protein-coding gene on chromosome 3 (32,237,207 to 32,370,699, forward strand). Ensembl gene ENSG00000170293.
Subcellular location: Membrane (Isoform 1); Cytoplasm (Isoform 2); Nucleus
Subcellular location (Human Protein Atlas): Nucleoplasm
Gene Ontology:
Molecular function: protein binding; structural constituent of myelin sheath
Biological process: myelination
Cellular component: membrane; cytoplasm; nucleus
Genetic constraint (gnomAD): Loss-of-function variants: 7 observed, 11.56 expected, observed/expected ratio (o/e) 0.61, 90% interval 0.34 to 1.14. The upper end of that interval is the gene's LOEUF score, 1.14, which puts it in group 4 of 6, group 1 being the genes least tolerant of losing a copy. Missense variants: 167 observed, 177.55 expected, observed/expected ratio (o/e) 0.94, 90% interval 0.83 to 1.07. Synonymous variants: 74 observed, 68.93 expected, observed/expected ratio (o/e) 1.07, 90% interval 0.89 to 1.3.
Homologues: Orthologues: chimpanzee CMTM8 (99% identical), dog CMTM8 (99% identical), macaque CMTM8 (98% identical), pig CMTM8 (98% identical), guinea pig CMTM8 (96% identical), rabbit CMTM8 (95% identical), mouse Cmtm8 (92% identical), rat Cmtm8 (91% identical), tropical clawed frog cmtm8 (65% identical), zebrafish cmtm8b (49% identical), zebrafish cmtm8a (45% identical), Caenorhabditis elegans F28H1.4 (27% identical), and 1 more. Paralogues in human: PLLP (41% identical), MAL (25% identical), CMTM4 (24% identical), MALL (24% identical), MAL2 (23% identical), CMTM7 (20% identical), PLP2 (17% identical), MARVELD1 (17% identical), CMTM1 (14% identical), CMTM6 (14% identical), CMTM2 (13% identical), CMTM5 (13% identical), and 2 more.
Diseases named in the same sentence as CMTM8 in open-access papers:
CMTM8 is named in the same sentence as 21 diseases in open-access papers, as found by Europe PMC text mining. Sharing a sentence is not in itself a finding about the gene and the disease. The quoted sentences say what the papers report.
gastric cancer (3 papers, 2021 to 2023). A primary or metastatic malignant neoplasm involving the stomach. "Another study showed that CMTM8 is down-regulated in gastric cancer, which is associated with poor prognosis." (PMID 35429970, 2022). "It has been previously documented that CMTM8 expression is reduced in several cancer types such as liver, lung, colon, rectum, esophagus, stomach cancers." (PMID 34978519, 2021). "CMTM8 was found to be downregulated in gastric cancer tissues rather than that in nontumor tissues, and the expression of CMTM8 was associated with metastasis of gastric cancer and prognosis of GC patients." (PMID 36975415, 2023).
osteosarcoma (3 papers, 2014 to 2019). A usually aggressive malignant bone-forming mesenchymal neoplasm, predominantly affecting adolescents and young adults. "The gene CMTM8 is reported as a candidate tumor suppressor gene in an osteosarcoma tumor model suppressing the activity of the oncogenic proteins c-Met and GPR177, however, its role in hematological tumors has not been reported." (PMID 27044543, 2016). "In osteosarcoma, it was demonstrated that CMTM8, also known as CKLFSF8, suppresses the EGFR signaling pathway." (PMID 25551557, 2014). "In osteosarcoma, CMTM8 has been shown to suppress EGFR signaling." (PMID 25551557, 2014). "We identified CMTM8 as a new candidate tumor suppressor gene and GPR177 as a new candidate oncogene in osteosarcoma." (PMID 25551557, 2014). "SNP in genes, such as PPP1R15A, PLA2G4C, CMTM8, and IFNL3, are responsible for the growth of various cancers, such as colorectal cancer, osteosarcoma, and hepatocellular carcinoma, but SNP in these genes may be associated with the pathogenesis of BRCA." (PMID 31311202, 2019).
pancreatic cancer (3 papers, 2022 to 2024). "Silencing CMTM8 suppressed, and its overexpression enhanced, the migratory and invasive capacity of human pancreatic cancer cell lines." (PMID 37345137, 2023). "Consistent with a role of CMTM8 in cancer progression, CMTM8-depleted human pancreatic cancer PANC-1 cells reduced the formation of metastatic lesions in the lung of nude mice relative to those produced by the parental cells." (PMID 37345137, 2023). "Some researchers have shown that the deletion of CMTM8 can inhibit the migration and invasion of pancreatic cancer, whereas high expression of CMTM8 can promote migration and invasion." (PMID 35429970, 2022). "Notably, reducing CMTM8 expression can lead to the inhibition of pancreatic cancer metastasis, thus establishing CMTM8 as a potential therapeutic target for pancreatic cancer." (PMID 38223763, 2024). "Furthermore, CMTM8 enhances the migration and invasion of pancreatic cancer cells, possibly through β-catenin signaling activation in pancreatic cancer cells, which in turn promotes pancreatic cancer invasiveness." (PMID 38223763, 2024). "CMTM8 can interact with LPA1, activating oncogenic β-catenin signaling as a potential therapeutic target for pancreatic cancer." (PMID 38223763, 2024).
colon cancer (2 papers, 2022 to 2025). "The GSE10950 dataset showed that CDKN2A and CMTM8 mRNA expression levels were up-regulated in colon cancer samples, while ILK was considerably down-regulated in colon cancer samples." (PMID 35429970, 2022). "To sum up, we found that CDKN2A and CMTM8 were up-regulated in colon cancer, while, ILK was down-regulated." (PMID 35429970, 2022). "We found that CMTM8 is highly expressed in colon cancer and leads to a poor prognosis." (PMID 35429970, 2022). "In contrast, the expression of CMTM8 was negatively correlated with CD8 + T cells, dendritic cells, and NK cells in colon cancer." (PMID 40179060, 2025). "We performed experiments in detecting protein expression of CDKN2A, CMTM8 and ILK by immunohistochemistry in the colon cancer tissues and adjacent tissues." (PMID 35429970, 2022). "Combined with our results, it can be inferred that the up-regulated CDKN2A, CMTM8, and down-regulated ILK may aggravate the progression of EMT by the TGF-β pathway in colon cancer, as a result, promoting the infiltration and metastasis." (PMID 35429970, 2022). "CDKN2A, CMTM8 and ILK are promising prognostic biomarkers and may be potential therapeutic targets in colon cancer." (PMID 35429970, 2022).
colorectal cancer (2 papers, 2019 to 2022). A primary or metastatic malignant neoplasm that affects the colon or rectum. "CDKN2A, CMTM8, ILK, and their co-expression genes were enriched in the following pathways: ILK pathway, TGF-β pathway, epithelial to mesenchymal transition in colorectal cancer, integrin-mediated cell adhesion, signaling by Notch, and so on." (PMID 35429970, 2022).
hepatocellular carcinoma (2 papers, 2014 to 2019). A malignant tumor that arises from hepatocytes. "In addition, in hepatocellular carcinoma cells and immortalized breast epithelial cells (MCF-10A), downregulation of CMTM8 was found to result in a transition from an epithelial to a mesenchymal phenotype." (PMID 25551557, 2014).
bladder cancers (1 paper, 2021). "A number of cancers such as liver, lung, colon, rectum, esophagus, stomach, and bladder cancers exhibited downregulation of CMTM8." (PMID 34978519, 2021). "Another study has reported that overexpression of CMTM8 suppresses cell proliferation and invasion in bladder cancer cells, indicating the involvement of CMTM8 in tumor metastasis." (PMID 34978519, 2021).
glioma (1 paper, 2022). A benign or malignant brain and spinal cord tumor that arises from glial cells (astrocytes, oligodendrocytes, ependymal cells). "The result indicated that the levels of CMTM3, CMTM6, CMTM7, CMTM8, and CKLF were much higher in IDH-WT than in IDH-mutated gliomas in the TCGA database (p < 0.001)." (PMID 35252165, 2022). "As illustrated, the expression of CMTM3, CMTM6, CMTM7, CMTM8, and CKLF in Grade II and III gliomas showed similar tendency as that in TCGA and CGGA databases." (PMID 35252165, 2022). "Results showed that the expression level of CMTM1, CMTM3, CMTM6, CMTM7, CMTM8, and CKLF was elevated in high-grade gliomas (grade III; p < 0.01)." (PMID 35252165, 2022). "In this study, it was found that CMTM6, CMTM7, CMTM8, and CKLF were highly expressed in grade III and IDH-WT gliomas." (PMID 35252165, 2022).
ovarian carcinoma (1 paper, 2022). A malignant neoplasm originating from the surface ovarian epithelium. "Surprisingly, through IHC experiments, the CMTM8 gene is abnormally highly expressed in ovarian cancer tissues compared with normal ovarian tissues." (PMID 36110202, 2022). "IHC verified that CMTM8 is highly expressed in ovarian cancer tissues and is closely related to Ki-67." (PMID 36110202, 2022). "In particular, CMTM8 may be related to the malignant proliferation and late clinical staging of ovarian cancer in addition to being an oncogene of ovarian cancer." (PMID 36110202, 2022). "The most important thing is that we found that CMTM8 can be used as an oncogene for ovarian cancer and may be related to its malignant proliferation." (PMID 36110202, 2022).
sarcoma (1 paper, 2014). A usually aggressive malignant neoplasm of the soft tissue or bone. "Interestingly, c-Met is known to be upregulated in human sarcomas.We found CMTM8 underexpression in a considerable number of cases in our original set and in the validation set." (PMID 25551557, 2014).
tumor (11 papers, 2014 to 2024). "CMTM8 gene expression is negatively correlated with tumor cell invasion/metastasis and markers of EMT in HepG2 cells." (PMID 32944388, 2020). "In other tumor types, CMTM8 is known to suppress the activity of the oncogenic protein c-Met and GPR177 is known as an overexpressed upstream regulator of the Wnt-pathway." (PMID 25551557, 2014). "In several tumor types, indications have been found for a tumor suppressor function of the CMTM8 gene product." (PMID 25551557, 2014). "Additionally, low expression of CMTM8 is correlated with higher tumor grades and TNM stages in bladder cancer." (PMID 32944388, 2020). "In other tumor types, overexpression of CMTM8 has been shown to result in tumor cell apoptosis." (PMID 25551557, 2014). "Limited clinical evidence of the direct tumor suppressor functions of CMTM5, CMTM7 and CMTM8 has been presented to date." (PMID 32944388, 2020). "In our analysis eight new candidate tumor suppressor genes were identified, OXSR1 (3p22.2), BSG(19p13.3), NT5E(6q14.3), PLEKHG7(12q22), CMTM8(3p22.3), NETO2(16q12.1), ODZ3(4q35.1) and ERBB4(2q34)." (PMID 25551557, 2014). "While CMTM3, CMTM4, CMTM5, CMTM7, and CMTM8 are typically expressed in normal human tissues but downregulated or absent in many tumor cell lines, their decreased expression supports tumor cell proliferation and progression 22-26." (PMID 38495487, 2024). "Besides the known tumor suppressor genes DOCK5 and PTEN, genes OXSR1, BSG, NT5E, PLEKHG7,CMTM8, NETO2, ODZ3, and ERBB4 adhered to our criteria and were qualified as novel candidate tumor suppressor genes." (PMID 25551557, 2014).
cancer (7 papers, 2016 to 2023). A tumor composed of atypical neoplastic, often pleomorphic cells that invade other tissues. "The cellular function of CMTM8 has been associated with endocytosis of the EGFR, a receptor with tyrosine kinase activity, whose levels or activity are affected in many types of cancers." (PMID 37345137, 2023). "By the results above, we know that CDKN2A and CMTM8 were higher expressed in cancer tissues and the prognosis will be worse when they were up-regulated." (PMID 35429970, 2022). "It has been reported that some CMTM family members, such as CMTM7 and CMTM8 exert their roles in human cancers by influencing RTK and RTK-related signaling pathways." (PMID 27121055, 2016). "MAL (LUAD, THYM, and UCEC), MAL2 (BRCA, PAAD, and UCEC), and PLLP (KICH, KIRC, and UCEC) present strong correlations (p ≤ 0.001) in three types of cancer, and MALL (KIRC and PAAD), CMTM8 (KIRC and KIRP), and MYADM (LUSC and THYM) do so in two cancer types." (PMID 37345137, 2023). "In this study, we demonstrate that miR-582-5p overexpression suppresses CMTM8 expression in TNBC cells, suggesting a mechanism for the downregulation of CMTM8 in cancer." (PMID 34978519, 2021). "Therefore, CMTM8 acts as an attenuator of EGF-induced signaling by facilitating ligand-induced EGFR endocytosis and subsequent desensitization, indicating that the alteration of CMTM8 levels in cancer might affect EGFR signaling." (PMID 37345137, 2023).
CMTM8 also shares sentences with these, for which no sentence is quoted: adenoma (1 paper); atherosclerosis (1); autoimmune disease (1); breast carcinoma (1); corticotrope adenomas (1); COVID-19 (1); hematological tumors (1); stomach cancers (1); triple-negative breast carcinoma (1).